MMP2 (matrix metallopeptidase 2)
Diseases named in the same sentence as MMP2 in open-access papers (continued):
Sharing a sentence is not in itself a finding about the gene and the disease.
colon carcinoma (continued). "We further verified the effective compounds, by analysing the key genes MMP2, MMP9, and VEGFA in the VEGF-MMPs signalling pathway of colon cancer cells using real-time (RT)-PCR." (PMID 33228670, 2020). "Consistently, the combined treatment of Aspirin and Cisplatin obviously attenuated the expression of main EMT-related proteins N-cadherin, β-catenin, Vimentin, MMP2, MMP9, Snail and Slug in human colon cancer cells." (PMID 31905343, 2020). "To check this, we transfected pre-miR-21 in colon cancer LS174 cells and found a similar increase in MMP-2, MMP-9 and MMP-11, as was seen when cells were exposed to cancer cell-derived exosomes." (PMID 32427870, 2020). "Five SNPs, rs1799750 in MMP-1, rs243865 in MMP-2, rs11568818 in MMP-7, rs2252070 in MMP-13 and rs28366003 in MT2A has been studied in various cancers including breast, lung and colon cancer, but results were ambiguous." (PMID 32765800, 2020). "Western blots were used to survey the inhibitory ability of Lactobacillus CFS on the protein levels of MMP2, MMP9, and VEGFA in colon cancer cells." (PMID 33228670, 2020). "We show that HT29 colon cancer cells induced an increased expression of VEGF-A, PDGF-A and MMP2 in MCs." (PMID 30987352, 2019). "To validate the activity of miR-29a-3p on the abrogation of MMP2 by AXT, we generated miR-29a-3p-knockdown colon cancer cells by transfecting miR-29a-3p sponge construct." (PMID 31263239, 2019). "Classical MC mediators, such as PDGF-A, VEGF-A, and MMP-2 were significantly upregulated in CCS, suggesting that colon cancer cells potentially augment MC-mediated tumor growth, angiogenesis and invasion." (PMID 30987352, 2019). "We also observed that the expressions of common metastasis markers (MMP-2 and MMP-9) were significantly lower in miR-340 treated colon cancer cells than in control cells." (PMID 29435169, 2018). "Indirect downregulation of matrix metalloproteinase 2 (MMP2) and E-cadherin by miR-29a-3p through Krüppel-like transcription factors 4 (KLF4) was reported in colon cancer cells." (PMID 29599914, 2018). "Dong and co-workers showed that shRNA-mediated knockdown of MMP2 in HT-29 and SW480 colon tumor cells clearly reduced their invasion capabilities in Boyden-chamber assays." (PMID 30473751, 2018). "CD155 knockdown via shRNA lentiviruses inhibited colon cancers cell migration and invasion, with a reduction in the expression of FAK, Src and MMP‐2." (PMID 28816021, 2018). "It specifically inhibited the metastatic dissemination capability of colon cancer cells HT29, including the migration and invasion ability, and their adhesion to human endothelium through inhibiting integrin αvβ6, MMP-2, MMP-9, and ERK phosphorylation by HT29." (PMID 28634392, 2017). "Knockdown of OPN expression in human colon cancer cells suppresses cell proliferation, adherence, invasion, and expression of angiogenetic factors, such as VEGF, MMP-2, and MMP-9." (PMID 28505114, 2017). "OPN knockdown in a human colon carcinoma cell line by siRNA reduces vascular endothelial growth factor (VEGF), matrix metalloproteinase (MMP)-2, and MMP9, and suppresses colon cancer cell growth." (PMID 28505114, 2017). "In colon cancer, SCRN1 expression promoted exocytosis secretion of MMP2 and MMP, while silencing this gene reduced MMP2 secretion, inhibited cell proliferation and decreased invasion capability." (PMID 28191313, 2017). "Our results indicate that C3G silencing-mediated p38α hyperactivation increases MMP2 and MMP9 activities in MEFs and HCT116 colon carcinoma cells, which correlates with the effect on cell migration and invasion." (PMID 27286263, 2016). "1α,25(OH)2D3 also inhibited the secretion of MMP-2 and MMP-9 and increased expression of F-actin induced by TGF-β1/β2 in colon cancer cells." (PMID 27548154, 2016). "Down-regulation of eIF4E suppresses the expression of VEGF, MMP-2 and MMP-9 simultaneously in colon cancer." (PMID 27907907, 2016).
colon carcinoma (continued). "Among the MMP family members, MMP-2 and MMP-9 are molecules crucial for cancer invasion, and are highly expressed in breast and colon cancer cells." (PMID 24520272, 2014). "We suggested that CCR1+ bone marrow (BM)-derived cells are recruited to the microenvironment of disseminated colon cancer cells, and produce metalloproteinases MMP9 and MMP2, helping metastatic colonization." (PMID 25326065, 2014). "LEF1 knockdown reduced tumor cell viability, invasion capacity, and expression of MMP2 and MMP-9, but induced apoptosis in colon cancer cells." (PMID 24098538, 2013). "The effect of IL-1β and IP6 on the expression of mRNA of MMP-1, MMP-2, MMP-3, MMP-9, MMP-10, and MMP-13 and that of their tissue inhibitors TIMP-1 and TIMP-2 in colon cancer cells using real-time QRT-PCR assay was determined." (PMID 22415590, 2012). "Collectively, our study demonstrated that the integrin β1-ERK1/2 and -MMP2 signaling plays critical roles in PRL-3-promoted motility, invasion, and metastasis of colon cancer cells." (PMID 19930715, 2009). "Additionally, the treatment with punicalagin led to a suppression of MMP-2 and MMP-9 expression in colon cancer cells." (PMID 39858430, 2024). "Nevertheless, research has indicated that the mRNA, protein, and/or activity levels of two specific MMPs, MMP-2 and MMP-9, are significantly upregulated in CRC tissues (even 10-fold within the invasive regions of colon cancer specimens) compared to normal colonic mucosa." (PMID 39683504, 2024). "Furthermore, the downregulation of MMP-2 and MMP-9 by inhibiting ERK and NF-κB activity reduces colon cancer cell migration and invasion." (PMID 38438872, 2024). "Available studies reveal that MMP-2 and MMP-9 are involved in the aggressiveness of colon cancer." (PMID 39683504, 2024). "For instance, the remotion of the DNA methyltransferases Dnmt-1 and Dnmt-3b induces MMP-3 but not MMP-1 and MMP-2 transcription in colon cancer HTCT116 cells." (PMID 38069210, 2023). "In addition, it was able of inhibit the angiogenesis-critical matrix metalloproteinase 2 (MMP-2) and metalloproteinase 9 (MMP-9) activities in colon cancer cells." (PMID 37653887, 2023). "Furthermore, nuclear PKM2 was reported to regulate the production of TNF-α, IL-1β, MMP-2, and MMP-9 in colon cancer cells and to activate inflammasomes." (PMID 35256696, 2022). "Herein, we noticed that CA with Cal treatment could suppress MMP-2 and MMP-9 protein expression in HCT116 cell lines, which demonstrates that combinatorial treatment can be an anti-metastatic agent in colon cancer cells." (PMID 36235161, 2022). "In addition, in colon cancer cells, AKT2-HK2-NF-κB/HIF1α/MMP2/MMP9 axis increased the invasion, tumorigenesis, and metastasis of in vitro and promotes lung metastasis in nude mice in vivo." (PMID 35953860, 2022). "Finally, the activity levels of MMP2 and MMP9 in a cohort of colon cancer samples, including tissues and the corresponding sera, was also investigated by zymography." (PMID 34830271, 2021). "Likewise, Zhou and Ma described a decrease of invasion and migration as well as decreased MMP-2 and MMP-9 mRNA in SW620 colon cancer cells treated with GA." (PMID 34680113, 2021). "Finally, the activity levels of both MMP2 and MMP9 were investigated by zymography in 26 colon cancer tissues and paired normal tissues, as well as in the corresponding sera." (PMID 34830271, 2021). "Moreover, Endostar, a recombinant human endostatin, significantly inhibited the metastasis of colon cancer by reducing the phosphorylation of AKT and ERK, and inhibiting the expression of MMP-2 and MMP-9 protein." (PMID 34654351, 2021). "In our preliminary study, we detected serum VEGF, MMP-2, and MMP-9 in patients with colon cancer." (PMID 33747930, 2021). "Therefore, MMP-2, in addition to MMP-9, represents a potential target molecule for treating malignant colon tumors." (PMID 34885656, 2021).
colon carcinoma (continued). "Previous studies have shown that a number of dried fruit body Hericium erinaceus extractions could reduce the expression of MMP-2 and MMP-9 in human colon cancer and invasion through modulations of the phosphorylation of ERK, JNK, and p38 MAPK." (PMID 31680958, 2019). "Moreover, inhibition of HO-1 nuclear translocation by E64d counteracted the effect of EtOH on both MMP-2 and VEGF, thus markedly suggesting a role of Nrf2/HO-1 axis in colon cancer progression." (PMID 30974805, 2019). "They suggested that MMP-2, HIF-1α and VEGF might represent useful parameters for detection of early carcinogenesis and progression of colon carcinoma." (PMID 24153191, 2013). "Both mRNA levels MMP-2 and MMP-9 have been found to be overexpressed in colon carcinomas." (PMID 21859479, 2011). "Furthermore, in colon carcinoma cells, it has been found that tiazolidinediones, through ROS production and ERK activation, induce matrix metalloproteinase 2 (MMP2) and subsequently increase tumor cell invasion." (PMID 19609453, 2009). "Moreover, we found that the activity of MMP9 analyzed using zymography was slightly decreased in TMEM211-silenced cells compared to those in scramble cells, suggesting that TMEM211 might regulate MMP2 and MMP9 for metastasis in colon cancer." (PMID 37367036, 2023). "Additionally, the suppression of the matrix metalloproteinase-2 (MMP-2) and MMP-9 expression by Luteolin is another mechanism that has been shown to be related to the anticancer effects of Luteolin on colon cancer by inhibiting angiogenesis, a crucial factor for tumor progression." (PMID 36992138, 2023). "In the subsequent in vitro experiments, after LEMD1 was depleted, the proliferation of colon cancer cells was observably impeded, as accompanied with the declined protein levels of proliferation markers Ki-67 and PCNA and invasion- and migration-related factors MMP2 and MMP9." (PMID 35294319, 2022). "C26 colon carcinoma secretomes increased DDR1 phosphorylation in HSCs and KCs by collagen I. Inhibition of kinase activity by DDR1-IN-1 or mRNA silencing of DDR1 reduced HSCs secretion of MMP2/9 and chemoattractant and proliferative factors for LSECs and C26 cells." (PMID 33110221, 2020). "Therefore, we expect that CLSE may have anti-metastatic effects via regulation of E-cadherin, vimentin, MMP-2, and MMP-9 in colon cancer cells, and plan to undertake these experiments in the future." (PMID 29110726, 2017). "Combining these findings, where miR-29b is a negative regulator of metastasis and targets key player of metastasis MMP-2, and HAG induces miR-29b and suppresses MMP-2 expression, we asked the question if HAG functionally suppresses metastasis of colon cancer cells." (PMID 24130681, 2013). "Furthermore, kaempferol may play an anti-colon cancer role by regulating the expression of MMP1, MMP2, and MMP9 protein, thereby increasing the expression level of miR-339-5p to mediate PKM alternative splicing reversing aerobic glycolysis in colon cancer cells." (PMID 39221164, 2024). "Further studies indicated that expression of FAK, Src and MMP‐2 decreased significantly in CT26 and Sw620 cells after transfection with CD155 shRNA lentiviruses, suggesting that these molecules may be responsible for CD155‐induced colon cancer cell migration and invasion." (PMID 28816021, 2018). "The enzymatic activities of MMP2 and MMP9 were evaluated by zymography in a cohort of 26 surgical colon cancer tissues paired with non-tumoral adjacent tissue." (PMID 34830271, 2021). "There was no decrease in MMP-2 gene expression in miR-29b silenced DLD-1 and LOVO colon cancer cells when exposed to HAG, 24 h." (PMID 24130681, 2013). "There was induction of this MMP upon transwell co-cultivation of the colon cancer cells with the fibroblasts but in vivo growth did not lead to a similar increase in the metastatic tumour cells (C170HM 2), MMP-2 again being attributed to the stromal cells." (PMID 11401321, 2001).
colon carcinoma (continued). "Therefore, we next determined levels of endogenous miR-21 and ECM mediators in colon cancer cell line LS174 by RT-qPCR, and found a positive correlation between miR-21 and ECM mediators MMP-2, MMP-9, and MMP-11, but not between miR-21 and ECM inhibitor TIMP-2." (PMID 32427870, 2020). "We found that knockdown of LEF1 expression suppressed MMP2 and MMP-9 expression, but not MMP-7, indicating that the selective modulation of MMPs by LEF1 could have the biological significance in colon cancer progression." (PMID 24098538, 2013). "Moreover, knockdown of LEF1 expression could significantly decrease the levels of MMP-2 and MMP-9 protein, but not MMP-7 protein in shLEF1 cells compared to that of shNC colon cancer cells." (PMID 24098538, 2013).
colorectal cancer (180 papers, 1997 to 2025). A primary or metastatic malignant neoplasm that affects the colon or rectum. "In colorectal cancer, the co-culture of tumor associated macrophages and colorectal cancer cells elevates the generation of cancer-derived MMP-2 and MMP-9." (PMID 33043017, 2020). "B7-H3 was expressed in the cancer cell membrane and was associated with the T stage of colorectal cancer; it also showed a positive correlation with MMP2 and MMP9 expression in cancer tissues." (PMID 27145365, 2016). "MMP2 has been linked to several human cancers, including colorectal cancer previously." (PMID 35991579, 2022). "Moreover, we showed that the levels of 20S proteasomes in exosomes, MMP9+ and MMP9+/MMP2+/EMMPRIN+ exosome subpopulations in CD9-positive exosomes were significant for predicting colorectal cancer risk in CPPs." (PMID 33773551, 2021). "Furthermore, MnTE-2-PyP effectively suppressed colorectal cancer cell migration and invasion and the expression of MMP-2 and MMP-9 caused by TGF-β." (PMID 30931081, 2019). "A study among the Tunisian population reported that a higher intensity of MMP-2 staining may be associated with colorectal cancer progression and invasion." (PMID 29949618, 2018). "We examined the possibility that PXN expression could be associated with Bcl-2, pBcl-2-S87, and MMP2 expression in tumors from 190 colorectal cancer patients." (PMID 25826088, 2015). "We next examined whether PXN, Bcl-2, pBcl-2-S87, and MMP2 expression could be associated with the outcomes of patients with colorectal cancer." (PMID 25826088, 2015). "The results herein suggested that MMP-2 should be a protein associated with colorectal carcinoma (CRC) and promote CRC metastasis." (PMID 27907907, 2016). "5‐HT activates 5‐HTRs to initiate Wnt/b‐catenin signaling in order to promote the self‐renewal of colorectal cancer stem cells, integrin/Src/Fak‐mediated signaling, uPAR/MMP‐2 signaling, and zinc finger ZEB1 and Snail protein expression." (PMID 40937192, 2025). "This promotes the expression of metalloproteinases MMP-2/9, thereby enhancing the development and progression of colorectal cancer." (PMID 39948481, 2025). "In colorectal cancer, MMP2, IL1B, IFNG, and CD4 have significant infiltration relationships with many immune cells." (PMID 40868987, 2025). "Xiao and co-workers found genistein to inhibit mRNA and protein expression of MMP-2 in colorectal cancer cells." (PMID 39335164, 2024). "In colorectal cancer cells, quercetin lowered MMP-2 and MMP-9 activity, as confirmed by gelatin zymography." (PMID 39335164, 2024). "Recently, astaxanthin has been reported to increase the expression of miR-29a-3p and miR-200a in colorectal cancer, thereby targeting MMP2 and ZEB1 and eventually inhibiting the epithelial-mesenchymal transition of cancer cells." (PMID 38649975, 2024). "Higher MMP-9 serum levels have been related to Crohn’s disease relapses, while elevated plasma levels of MMP-2, -9 and -13 have been addressed as potential biomarkers of colorectal cancer." (PMID 38802341, 2024). "According to growing research, MMP-2 appears to also have a key role in the metastasis of a number of malignancies, including glioma and colorectal cancer." (PMID 37445754, 2023). "For example, matrix metalloproteinase 2 (MMP2) is involved in the progressive metastatic transformation of cancer cells, including colorectal cancers." (PMID 36765584, 2023). "PTGS2 is required in diseases, such as colorectal cancer, while MMP2 mostly plays a role in inflammatory responses and immune responses." (PMID 35227278, 2022). "Using colorectal cancer cell lines and zebrafish xenotransplant models, we found that deflamin exhibits anti-MMP-2 and anti-MMP-9 activity, being able to reduce tumor size and metastasis formation in vivo." (PMID 36551666, 2022). "MMP2 has been shown to be overexpressed in colorectal cancer tumors compared to normal tissues, and is associated with metastatic tumor phenotype and shorter survival times in colorectal cancer." (PMID 35991579, 2022).